SNX27 (sorting nexin 27)
Diseases named in the same sentence as SNX27 in open-access papers (continued):
Sharing a sentence is not in itself a finding about the gene and the disease.
breast tumor (1 paper, 2019). "Here, we have demonstrated that SNX27 plays a novel and crucial role in breast tumor cell growth." (PMID 31182056, 2019).
colon cancer (1 paper, 2025). "Some members, such as SNX1, SNX6, and SNX27, have oncogenic properties, promoting proliferation and metastasis by activating the TGF-β signaling pathway and recycling cancer-associated proteins in gastric, pancreatic, and colon cancer, respectively." (PMID 40810725, 2025).
diabetes (1 paper, 2022). "As the normal cargo sorting function of SNX27 was inhibited, numerous human physiology conditions relying on SNX27 including hypertension, diabetes, neuronal regeneration, copper transport and glucose transport would be disrupted." (PMID 36225258, 2022).
hepatocellular carcinoma (1 paper, 2021). A malignant tumor that arises from hepatocytes. "Among them, ubiquitin-like with PHD and ring finger domains 1 (UHRF1) and sorting nexin 27 (SNX27) with a fold change >2, revealing significantly high expression in hepatocellular carcinoma." (PMID 34249673, 2021). "UHRF1 and SNX27 were host genes of exosomal circRNA that showed more than two-fold difference in expression in hepatocellular carcinoma." (PMID 34249673, 2021).
hereditary spastic paraplegia (1 paper, 2018). Hereditary spastic paraplegias (HSP) comprise a genetically and clinically heterogeneous group of neurodegenerative disorders characterized by progressive spasticity and hyperreflexia of the lower limbs. "Finally, we summarize the roles of SNX27 and the retromer complex in other neurodegenerative diseases, including Down’s syndrome (DS), hereditary spastic paraplegia (HSP) and neuronal ceroid lipofuscinoses (NCLs)." (PMID 29632483, 2018).
Hypercalcemia (1 paper, 2020). An abnormally increased calcium concentration in the blood. "Interestingly, SNX27 protein abundance was significantly decreased in the kidney inner medulla of rats with lithium-induced NDI, suggesting that autophagy could, at least in part, be involved in the downregulation of AQP2 in NDI, as demonstrated in the hypokalemia or hypercalcemia model." (PMID 32413996, 2020).
liver cancer (1 paper, 2019). An epithelial or non-epithelial malignant neoplasm that arises from the liver. "We found COLEC10, GPAA1, CD5L, NCSTN, SNX27, GOLPH3L, and HIST2H2AC genes were associated with worst OS (HR < 1) in female liver cancer patients." (PMID 31216110, 2019).
lung carcinoma (1 paper, 2015). "We have therefore evaluated whether SNX27 and MYO18A also regulate lung cancer cell motilities through the PIX/GIT1 complex." (PMID 26462147, 2015).
nephrogenic diabetes insipidus (1 paper, 2020). Nephrogenic diabetes insipidus (NDI) is characterized by polyuria with polydipsia, recurrent bouts of fever, constipation, and acute hypernatremic dehydration after birth that may cause neurological sequelae. "Lithium-induced nephrogenic diabetes insipidus in rats revealed a significant downregulation of SNX27 in the kidney inner medulla." (PMID 32413996, 2020).
tauopathy (1 paper, 2025). Neurodegenerative disorders involving deposition of abnormal tau protein isoforms (tau proteins) in neurons and glial cells in the brain. "Dysregulation of SNX27, including its altered expression profile, has not been reported in terms of tauopathy." (PMID 39974971, 2025).
tuberculosis (1 paper, 2019). A chronic, recurrent infection caused by the bacterium Mycobacterium tuberculosis. "In addition to circRNA-100338, hsa_circ_0014186, another circRNA isoform of SNX27, was down-regulated in human plasma with active tuberculosis, however, the function of other circRNA isoforms was still unknown, suggesting that further studies were needed to characterize the FUNCTION of circRNAs." (PMID 31157168, 2019).
tumor (9 papers, 2016 to 2023). "Retromer complex assembly on endosomal membranes is modulated by the ovarian tumor DUB with linear linkage specificity (OTULIN) whose recruitment by SNX27 antagonizes the interaction between SNX27 and VPS26 and thus inhibits cargo loading." (PMID 36825571, 2023). "Our results suggest the SNX27 regulates E-cadherin, one of the tumor suppressors, thus decreasing cell proliferation." (PMID 31182056, 2019). "To elucidate the mechanism of how SNX27 knockdown impacted the tumor cell behavior and phenotype, we assessed the effect of SNX27 knockdown on biomarkers of EMT." (PMID 31182056, 2019). "In a xenograft nude mouse model, we found that knockdown of SNX27 significantly inhibited tumor growth." (PMID 31182056, 2019). "SNX27 KD significantly reduced the amount of Claudin-5 and decreased the cell-to-cell tight junctions that made the tumor cells “glue” together." (PMID 31182056, 2019). "Our findings provide insights into manipulating SNX27 as a new target gene to control tumor growth and development." (PMID 31182056, 2019). "Given the effect of the TEX264 and SNX27 interaction on tumor cell migration, development of drugs that block this interaction could inhibit tumor invasion and metastasis in vivo." (PMID 35837377, 2022). "In this scenario, it was feasible that SNX27 downregulation in Kidins220f/f mice could lead to lysosomal processing of AQP4 in astrocytes, as it occurs with Kidins220 after SNX27 loss in tumour cells." (PMID 34002021, 2021). "Multiple studies have suggested how SNX27 affects tumor growth both in vitro and in vivo." (PMID 33937239, 2021). "Our data have demonstrated that SNX27 plays a crucial role in tumor growth in vitro and in vivo." (PMID 31182056, 2019). "We showed that knockdown of SNX27 could reduce tumor cell migration, enhance the cell-cell contacts, and suppress cancer growth." (PMID 31182056, 2019). "SNX27 may mainly affect tumor cell EMT by altering the expression of EMT-regulating proteins, thus reducing the tumor growth and migratory properties." (PMID 31182056, 2019). "Together, our results reveal a fundamental role of PTEN in the regulation of the SNX27 retromer pathway, which governs glucose transport and might contribute to PTEN tumor suppressor function." (PMID 29117568, 2017). "An RNAi screen conducted in primary AML cells reported that SNX27 promotes AML tumorigenesis and may serve as a potential prognostic marker, since a lack of SNX27 dramatically reduces tumor cell growth and viability." (PMID 36612066, 2022).
cancer (8 papers, 2016 to 2025). A tumor composed of atypical neoplastic, often pleomorphic cells that invade other tissues. "This review is aimed towards summarizing scientific evidence supporting and providing an update on the current molecular understanding of SNX27, its associations with the sorting and transport of internalized endosomal cargo, and its implication in cancers." (PMID 36612066, 2022). "SNX27 is further linked to addiction via its role in potassium channel trafficking, and its over-expression is linked to tumorigenesis, cancer progression, and metastasis." (PMID 33937239, 2021). "Future exploration should clarify the underlying cellular functions of SNX27/retromer in the context of specific cancer cells." (PMID 33937239, 2021). "Although the direct mechanisms remain to be poorly understood, these studies suggest that SNX27 associations may influence cancer cell proliferation and survival by regulating intracellular energy levels." (PMID 36612066, 2022). "It is important to identify cancer-associated proteins that may interact with the PDZ-domain in a SNX27-dependent recycling and such proteins could be targeted to impair tumorigenesis." (PMID 36612066, 2022). "The knockdown of SNX27 resulted in a loss of aggressiveness of cancer cells in vitro and in vivo." (PMID 31182056, 2019). "Human genome database analysis reveals that SNX27 is highly expressed in several cancers, in particular invasive breast cancer, which is inversely correlated with overall patient survival." (PMID 36612066, 2022). "In this review we provide a summary of the current knowledge, as supported by scientific literature and evidence, regarding the fundamental structure, biological function, and implication of SNX27 in human cancers." (PMID 36612066, 2022). "We further reported a novel role of SNX27 in reducing aggressiveness and invasive capacity of the cancer cells via the modulation of EMT marker Vimentin, and cell–cell junction markers, such as Claudin-5 and E-cadherin." (PMID 36612066, 2022). "In this review, we summarize the structure and fundamental roles of SNX proteins, with a focus on SNX27, and provide the current evidence indicating towards the role of SNX27 in human cancers." (PMID 36612066, 2022). "Insights into the emerging roles and mechanism of SNX27 in cancers will provide better development strategies to prevent and treat tumorigenesis." (PMID 36612066, 2022). "The roles of SNX27 in cancer is largely unexplored, however many of its identified cargoes have been indicated in tumorigenesis." (PMID 36612066, 2022). "Observations from previous studies indicate a potential therapeutic strategy of targeting SNX27 for cancer treatment, however further research is required to fully elucidate the role of SNX27 in tumorigenesis." (PMID 36612066, 2022). "SNX27 affects nutrient uptake in cancer cells through recycling of different energy transport receptor proteins." (PMID 33937239, 2021). "To elucidate the mechanism of how knocking down SNX27 leads to suppressed cancer cell proliferation and migration, we investigated the expression of EMT marker proteins." (PMID 31182056, 2019). "In conclusion, we have demonstrated a novel function for SNX27 in regulating the growth of cancer cells." (PMID 31182056, 2019). "Overall, SNX27 may serve as an important target based on its established roles in promoting tumorigenesis, cancer progression, and metastasis." (PMID 33937239, 2021). "In the future, we will also plan to determine the role of SNX27 in other cancer cells." (PMID 31182056, 2019). "Our data indicated that SNX27 may play a crucial role in cancer cell proliferation, which is consistent with previous reports that SNX27 is required for HeLa and mpkCCD cell migration." (PMID 31182056, 2019). "In the current study, we hypothesized that reduction of SNX27 in cancer cells suppresses proliferation." (PMID 31182056, 2019).
cancer (continued). "Therefore, our results exploit a novel physiological function of SNX27 in cancer development, which must be interesting for further investigations." (PMID 26744382, 2016). "However, there are limited studies on the tissue-special roles of SNX27 in various cancers." (PMID 36612066, 2022). "Increasing evidence suggests that SNX27 may mediate cancer development and/or progression as it influences distinct protein–protein interactions, membrane remodeling, and cell surface expression of several important tight junction proteins and receptors implicated in cell signaling pathways." (PMID 36612066, 2022). "Thus, our data suggest that SNX27 plays a critical role in cancer development." (PMID 31182056, 2019). "However, the mechanisms by which SNX27 functions in different cancers overall remain unclear." (PMID 33937239, 2021). "Finally, SNX27 is involved in cellular uptake of specific amino acids like glutamine, as well as mTORC1 activation, which may affect how cancer cells proliferate." (PMID 33937239, 2021). "SNX27 governs glucose transport by an interaction with phosphatase and tensin homolog deleted on chromosome 10 (PTEN); this prevents glucose transporter type 1 (GLUT1) accumulation at the cell surface and suppresses cancer progression." (PMID 33937239, 2021).
infection (8 papers, 2018 to 2025). The state of being infected such as from the introduction of a foreign agent such as serum, vaccine, antigenic substance or organism. "This study investigated the sorting nexin 27 (Snx27) gene encoded by the orange-spotted grouper (Epinephelus coioides) on RGNNV infection in grouper kidney cells." (PMID 39494909, 2024). "Considering the regulation of ACE2 by SNX27, SNX27 could recycle more ACE2 to the cell surface, causing cell susceptibility to SARS-CoV-2, and SNX27 may play a proviral role during infection." (PMID 35022217, 2022). "However, knockdown of SNX27 only causes a marginal reduction in infection, but, interestingly, knockdown of both SNX17 and SNX27 results in significant reduction in infection, greater than the effect observed for SNX17 knockdown alone." (PMID 30181457, 2018). "As infection progresses, i.e. at 4-6 hpi, SNX27 dependence increases, coinciding with the timing of the onset of tubulation events associated with the establishment of pre-AC, and progresses during infection, as shown by the effects on pM57, viral DNA replication and L gene expression." (PMID 39359939, 2024). "As infection progressed and the pre-AC matured into the AC, the colocalization of SNX27 with SNX3 further increased, suggesting that the area for recycling CIE cargo within the AC is continuously expanding." (PMID 40299528, 2025). "SNX27 requirement was observed very early in infection and intensifies as the MCMV cycle progresses, eventually leading to a decrease in L gene expression and in release of infectious virions to a comparable magnitude." (PMID 39359939, 2024). "Essentially, the same results were obtained in the NIH3T3 cell line with inducible expression of EGFP-SNX27 as in Balb3T3 cells, since infection in Balb3T3 cells increased the visualization of endogenous SNX27 through its retention on membranous structures." (PMID 39359939, 2024). "To distinguish whether the observed effects of SNX27 depletion are associated with its contribution to the SNX27:Retromer:ESCPE-1 complexes, we examined the effect of Vps35 and SNX1 + 2 depletion on the expression of pM74 in the L phase of infection." (PMID 39359939, 2024). "Therefore, SNX27-retromer complex employs a universal mechanism to regulate the infection of SARS coronaviruses that use ACE2 as a common receptor." (PMID 35022217, 2022). "We next examined the infection by disturbing the expression level of SNX27." (PMID 35022217, 2022). "Therefore, it is likely that SNX27/Retromer/ESCPE-initiated tubulation within the pre-AC provides signaling platform that is essential for the surplus of MCMV gene products required for lytic infection." (PMID 39359939, 2024). "Compared to the siNC, the depletion of SNX27 enhanced the SARS-CoV-2 pseudovirus infection, whereas the KD of ACE2 dramatically reduced the infection." (PMID 35022217, 2022). "To date, there is no known mechanism of HTLV-1 receptor molecule regulation post infection, and our work suggests that Tax-1 is capable of regulating GLUT1 localization through its interaction with SNX27." (PMID 30897179, 2019). "At the end of the E phase of infection, at 16 hpi, SNX27 and SNX3 were concentrated at the same vacuolar structure and likely at the same membrane domains, as colocalization was significantly higher than at the beginning of infection." (PMID 40299528, 2025). "It acts sequentially with SNX27, SNX4, and SNX17 along the recycling pathway in the process of the production and release of infection virions, suggesting that multiple membrane sources may contribute to the secondary envelopment of MCMV virions." (PMID 40299528, 2025). "Thus, we first used confocal imaging to investigate the distribution of SNX27, Vps35 and SNX1 in the early phase of infection." (PMID 39359939, 2024). "Indeed, depletion of VPS35 also contributed the increased infection of SARS-CoV-2 pseudovirus, although the effect of VPS35 KD is less than that of SNX27 KD." (PMID 35022217, 2022).
neurodegenerative disease (5 papers, 2020 to 2025). A disorder of the central nervous system characterized by gradual and progressive loss of neural tissue and neurologic function. "Mechanistic study of the function and evolution of the SNX27:Retromer:ESCPE-1 assembly provides new insight into pathway defects associated with neurodegenerative disease and an interesting comparison with the yeast pentameric Retromer." (PMID 35417450, 2022). "Importantly, defects in SNX27–Retromer function are associated with the pathoetiology of human disease most notable neurological disorders and neurodegenerative disease." (PMID 35417450, 2022). "Therefore, dysregulated SNX27 functioning has been reported in several neurodegenerative diseases, such as AD." (PMID 39974971, 2025). "Therefore, dysregulated expression of SNX27 can lead to seizures and epilepsy among a plethora of other neurodegenerative diseases." (PMID 36612066, 2022). "Whether SNX27/retromer may be a putative therapeutic target to prevent neurodegenerative disease is now an emerging area of study." (PMID 33937239, 2021). "Given that synaptic dysfunction and endo-lysosomal dysregulation represent the pathological features in neurodegenerative diseases, such as Alzheimer’s disease (AD) and Down’s syndrome (DS), the role of SNX27 in these diseases has attracted extensive attention." (PMID 33330482, 2020).
neurological diseases (5 papers, 2016 to 2021). "Sorting nexin 27 (SNX27) is an endosomal adaptor protein associated with a variety of nervous system diseases, and it is mainly responsible for the trafficking of postsynaptic membrane receptors." (PMID 33330482, 2020). "Sorting nexin 27 (SNX27) is an endosome-associated cargo adaptor that is involved in various pathologies and development of neurological diseases." (PMID 30619032, 2018). "Sorting nexin 27 (SNX27) is an endosome-associated cargo adaptor that is involved in the development and pathologies of neurological diseases." (PMID 30619032, 2018). "Our finding that the SNX27–retromer–WASH complex mainly conducts the endosomal sorting pathway will likely clarify cellular mechanisms underlying these neurological disorders." (PMID 26956659, 2016). "Together, these findings demonstrate the vital role of SNX27 in neurological disorders and neuropathic injuries such as SCI." (PMID 30619032, 2018). "Despite its well-characterized roles in various neurological disorders, the role of SNX27 in SCI remains unclear." (PMID 30619032, 2018).
SNX27 also shares sentences with these, for which no sentence is quoted: cervical cancer (3 papers); autism (2); chlamydial infection (1); Gliosis (1); Hypertension (1); Hypokalemia (1); Menkes disease (1); mood disorder (1); neurodevelopmental disorder (1); schizophrenia (1); spinal cord injury (1); Ventriculomegaly (1).